CTLA4 (cytotoxic T-lymphocyte associated protein 4)
Diseases named in the same sentence as CTLA4 in open-access papers (continued):
Sharing a sentence is not in itself a finding about the gene and the disease.
cancer (continued). "The anti-CTLA4 and anti-PD-1 immunotherapies have emerged as promising options for cancer therapy." (PMID 34686691, 2021). "For the first time, we have described CTLA-4 expression on CTCs in cancer, a checkpoint that is known to be expressed on immune cells and pituitary cells relevant to the known efficacy and toxicity of CTLA-4 blockade in men, and which has been reported to be expressed on some cancer cell lines." (PMID 33602330, 2021). "Suppression of T-cell activation by PD-1 and CTLA-4 is considered a major escape mechanism of cancer cells, and inhibition of these proteins by ICIs successfully activates the immune system to identify and eliminate cancer cells." (PMID 35047501, 2021). "CTLA4 is a negative regulator of T cell activation and its inhibition allows T cells’ response against cancer; likewise, also the PD-1 axis is involved in the negative T cell regulation and its inhibition leads to the recovery of the cytotoxicity of T cells towards tumors." (PMID 33925884, 2021). "Concerning novel anti-cancer drugs, checkpoint inhibitors (CPIs) reactivate T lymphocytes to recognize cancer cells by blocking cytotoxic T-lymphocyte antigen-4 (CTLA-4) or programmed death-1 (PD-1) but may induce several immune-related adverse effects." (PMID 33810369, 2021). "In addition to the PDL pathway, cancer cells can also inhibit the activation of lymphocytes and lead them to apoptosis by expressing molecules that bind to CTLA-4 (cytotoxic T-lymphocyte antigen 4), an inhibitory receptor present on the surface of lymphocytes." (PMID 35008287, 2021). "Interestingly, the response of MCF-7 cancer cells to CTLA-4 blockage was significantly different compared to the MDA-MB-231 cell line." (PMID 34440813, 2021). "In addition, immune checkpoints block (ICB) treatment has become a new method to treat all kinds of cancers, especially the study of CTLA-4 and PD-1/PD-L1 molecules." (PMID 34778054, 2021). "It is thought that only certain patients are eligible for immunotherapy: those presenting with either high expression levels of CTLA-4 and PD-1 receptor ligands on cancer/stromal cells, or increased amounts of the immune checkpoint inhibitor receptors on immune cells." (PMID 34357131, 2021). "However, various clinical trials by immunotherapy (anti-PD1 and anti-CTLA4) have only shown modest clinical outcomes in comparison to other cancers." (PMID 34573332, 2021). "Clinical studies showed that the CTLA-4 inhibitor could significantly prolong the survival time of patients with malignant tumors." (PMID 34553071, 2021). "Immunotherapy using anti-PD-1/PD-L1 and anti-CTLA4 has become a breakthrough in cancer treatment." (PMID 33936117, 2021). "Besides, the primary immunodeficiency pathway (KEGG), CTLA4 pathway (Biocarta), and cancer immunotherapy by PD1 blockade (WP) were highly enriched in the high-risk group, indicating that immune checkpoints play a role in GBM immune evasion." (PMID 35111196, 2021). "ICIs have drastically improved cancer treatments, and to date, 7 ICIs, namely, nivolumab, pembrolizumab, and cemiplimab for PD-1; avelumab, atezolizumab, and durvalumab for PD-L1; and ipilimumab for CTLA-4, were approved by the US FDA." (PMID 34369137, 2021). "However, it is still unclear the mechanism of CTLA-4 autophagic degradation and the effect on cancer immunotherapy." (PMID 34493296, 2021). "Furthermore, we analyzed the correlation between PSME genes and the expression of immune checkpoint-relevant genes, including PD-L1, PD-1, LAG3, and CTLA4, in 33 cancer types in TCGA database." (PMID 34650966, 2021). "In summary, our data indicated that cancer patients with low Casp8 expression might benefit the most from anti‐PD‐1 or anti‐CTLA‐4 immunotherapy." (PMID 33934451, 2021). "Downregulation of Casp8 in both the cancer cells and/or NK cells may lead to severe immune tolerance because of the upregulation of PD‐L1 and/or PD‐1 and CTLA‐4." (PMID 33934451, 2021).
cancer (continued). "Ipilimumab (Yervoy®) developed by Medarex (Princeton, NJ, USA), is a fully humanized monoclonal antibody that binds to the ECD of CTLA-4, specifically blocks the interaction between CTLA-4 and B7-1 or B7-2, and eventually maintains T-cell cytotoxicity to attack cancer cells." (PMID 33466394, 2021). "The mAb which targets PD-1 and CTLA-4 are the most extraordinary examples of cancer immunotherapy." (PMID 33492335, 2021). "Several co-inhibitory receptors have been identified in cancer, including PD-1, CTLA-4, T-cell immunoglobulin and mucin domain 3 (Tim-3), lymphocyte-associated gene 3 (LAG3), B and T lymphocyte attenuator (BTLA), and T-cell immunoglobulin and ITIM domain (TIGIT), called immune checkpoints." (PMID 34332576, 2021). "This technique aims to block the overexpressing programmed cell death-1 (PD-1) in T cells and programmed cell death ligand-1 (PD-L1) in cancer cells, with the cytotoxic T lymphocyte antigen-4 (CTLA-4) protein receptors acting as checkpoints for cancer treatment." (PMID 35056967, 2021). "Among many ICIs identified, anti-PD1/PD-L1 and anti-CTLA-4 are currently approved for clinical application, and combination treatment of anti-PD1 and anti-CTLA-4 could have synergistic effect in some kinds of cancer." (PMID 34381735, 2021). "Immune checkpoint inhibitors (ICI) are monoclonal antibodies that block these pathways by binding to the PD-1 receptor (i.e., nivolumab, pembrolizumab), to PD-L1 (i.e., atezolizumab), or to CTLA-4 (i.e., ipilimumab) and thus enhance the immune response against cancer cells." (PMID 33142689, 2020). "Notably, the current use of immune checkpoint inhibitors to target immune checkpoint receptors such as CTLA-4 or PD-1 has led to remarkable treatment responses in a variety of cancers." (PMID 32545182, 2020). "The use of vancomycin prior to anti-CTLA-4 therapy shows promise for future cancer treatments." (PMID 32944086, 2020). "Therefore, the blockade of the inhibitory effects of CTLA-4 on T cells-mediated immune response is used to abolish immunological tolerance in the treatment of some types of cancer." (PMID 32316552, 2020). "When CTLA-4 Ab is frequently administered over long periods of time when treating malignancy." (PMID 32075963, 2020). "Since 2011, the FDA approved six ICIs—ipilimumab (anti-CTLA-4), nivolumab (anti-PD-1), pembrolizumab (anti-PD-1), atezolizumab (anti-PD-L1), avelumab (anti-PD-L1), and cemiplimab (anti-PD-1)—for the treatment of more than 15 different types of cancer." (PMID 33086754, 2020). "CTLA-4 antibody ipilimumab was the first ICI therapy to be accepted for the treatment of cancer." (PMID 31952311, 2020). "On account of the increasing importance of immune system in tumorigenesis, CTLA4 may play an indispensable role in cancer therapy." (PMID 31894857, 2020). "Indeed anti-PD-1 and CTLA-4 immunotherapy have had success in the clinic and become standard of care cancer treatment approaches." (PMID 32259744, 2020). "However, several mechanisms are involved in immune system homeostasis as well as in cancer immune tolerance and immune-resistance, and some patients differ in PD-1 or CTLA4 expression, so different strategies are under study in clinical oncology." (PMID 33086484, 2020). "Cytotoxic T lymphocyte-associated antigen-4 (CTLA-4) is another immune checkpoint that can impair T-cell function and Ipilimumab (an anti-CTLA-4 antibody) was the first immune checkpoint inhibitor approved for the treatment of cancer." (PMID 33072081, 2020). "Ipilimumab (Anti-CTLA-4), Pembrolizumab, Nivolumab (Anti-PD-1), and Atezolizumab, Durvalumab, Avelumab (Anti-PD-L1) have shown significant efficacy in clinical and clinical trials, and have been approved for treating a number of cancers." (PMID 33344447, 2020). "Antibodies targeting CTLA-4 or PD-1/PD-L1 are effective in treating a variety of malignant tumors." (PMID 32754579, 2020).
cancer (continued). "In addition to PD-1, there are other immune suppressive checkpoint molecules that dampen cytotoxic T- cell activity against cancer cells—NRP-1, cytotoxic T-lymphocyte associated protein -4 (CTLA-4), TIM-3, LAG 3, and VISTA." (PMID 33256089, 2020). "Immune checkpoint inhibitors (ICIs) targeting cytotoxic T-lymphocyte antigen-4 (CTLA-4) or programmed cell death-1 (PD-1) pathways are reshaping the landscape of cancer therapy, yielding unprecedented clinical success in treating multiple cancer types." (PMID 32306958, 2020). "Widely utilized cancer immunotherapy approaches include immune checkpoint blockade therapy directed against immune checkpoint proteins (e.g., PD-1, PD-L1, CTLA-4, TIM-3, VISTA), chimeric antigen receptor T (CAR-T) cells, dendritic cell vaccines, and cytokines, among others." (PMID 32545182, 2020). "First, our study was only a bioinformatic and pan‐cancer analysis of anti‐CTLA4 treatment." (PMID 32810393, 2020). "CTLA4 also plays an important role in cancer progression, prognosis, and proliferation." (PMID 33014010, 2020). "In addition to the well-recognized immune checkpoint blockers, such as CTLA-4 and PD-1, this type of immune blocker awaits for investigation of its involvement in cancer." (PMID 33343635, 2020). "Numerous trials are exploring immunotherapy combination approaches in advanced cancers with a backbone of PD‐1/PD‐L1/CTLA4 inhibition in conjunction with Treg cell focused agents including those targeting the Inducible T cell Co‐Stimulator (ICOS) receptor (NCT02723955), and GITR (NCT03126110)." (PMID 32383556, 2020). "Preliminary data from a phase 2 basket study of ipilimumab and nivolumab in rare cancers suggest that a combination of CTLA-4 and PD-1 inhibition may yield a higher response rate than pembrolizumab monotherapy." (PMID 32152503, 2020). "This hypothesis is supported by an increasing number of reports that show a positive correlation between eosinophilia and clinical response to anti-PD-1 and anti-CTLA-4 in cancer patients." (PMID 33329534, 2020). "In the past few decades, critical breakthroughs have been made in the field of immune surveillance, including the involvement of PD-1/PD-L1 and CTLA-4 signaling pathways in the development and progression of cancers, which plays a vital role in the regulation of immune responses." (PMID 33553243, 2020). "ICIs such as PD-1/PD-L1 and CTLA4 antibodies, are widely applied in several cancers, and studies have indicated that ICI treatment could enhance the effect of ablation." (PMID 32847533, 2020). "The approval of immune checkpoint inhibitors (such as CTLA-4 or PD1/PD-L1 inhibitor antibodies) in the treatment of cancers has changed the outcome of several of such severe diseases and highlighted the strong molecular crosstalk between the microbiota and the immune system." (PMID 32793150, 2020). "Therefore, newly proliferated multi-clonal cancer antigen-specific T-cells that are induced by NIR-PIT can be further activated with CTLA4 checkpoint inhibition." (PMID 32937841, 2020). "A study showed that drugs blocking and deactivating CTLA4 could help T cells find and attack cancer cells and proved to be effective in cancer treatment." (PMID 31894857, 2020). "It would be interesting to study whether Tet2 might be involved in CTLA-4 or PD-1 pathway-mediated immune checkpoint inhibition for cancer treatment." (PMID 33184433, 2020). "Ipilimumab was the first ICB targeting CTLA-4 to be approved by FDA for cancer treatment." (PMID 32158356, 2020). "Immune checkpoint inhibitors target specific pathways such as CTLA4 and PD-1, and have shown remarkable success against melanoma, non-small-cell lung cancer, and Hodgkin’s lymphoma, with mixed results in several other cancers." (PMID 32899865, 2020).
cancer (continued). "To identify a transcriptomic signature for clinical responsiveness of the anti-CTLA-4 currently used in clinic, ipilimumab, we compared immunological signature scores from cancer transcriptome data using single sample gene set enrichment analysis (ssGSEA) with six defined immunological gene sets." (PMID 31991588, 2020). "The clinical outcome in cancer treatment has significantly improved in some patient cohorts since immune-checkpoint inhibitors (ICIs) are used in the clinics, like those targeting the PD-1/PD-L1 and CTLA-4 axes." (PMID 32349284, 2020). "For example, cancer could enhance the expression of the CTLA-4, and thus downregulate anti-tumor T-cell responses." (PMID 33297561, 2020). "CTLA-4 upregulation in cancer patients is recognized as an important mediator of immune evasion." (PMID 32850353, 2020). "In addition, combination therapy of tyrosine kinase inhibitors, such as FGFR and CFS1R inhibitors, with anti-PD-1 or anti-CTLA-4 antibodies showed promising benefit for cancer patients." (PMID 33005178, 2020). "Immune checkpoint inhibitors (ICIs), such as PD-1/PD-L1 and CTLA4 antibodies, have been widely applied in several cancers, and studies have indicated that ICI treatment could enhance the effect of ablation." (PMID 32847533, 2020). "In several types of cancer, the receptor CTLA-4 is expressed by activated T cells, where it binds to B7 and prevents its interaction with CD28, consequently decreasing the regulation, leading to a negative regulation of T cell proliferation and IL-2 production." (PMID 32344813, 2020). "Furthermore, correlations between the two PDEIRGs (BIRC5 and LPA) and immune checkpoints of cancer treatment (such as CTLA4, PD-1, and PD-L1) were demonstrated." (PMID 33195412, 2020). "Taken together, our findings provided clues for the roles of PD-1 and CTLA4 in cancer immunity." (PMID 33072070, 2020). "Recently, cancer immunotherapy, particularly immune checkpoint therapy targeting programmed cell death-1 (PD-1), PD-1-ligand-1 (PD-L1), and cytotoxic T-lymphocyte antigen 4 (CTLA-4), has become a new treatment option for various types of cancers." (PMID 32859106, 2020). "Finally, a novel expression signature based on the overexpression of MAGE-A cancer germline antigens has been reported as a putative specific predictor of resistance to anti-CTLA4 treatment." (PMID 31968651, 2020). "Retrospective analysis of the efficacy of anti-CTLA-4, anti-PD-1, and/or anti-PD-L1 in more than 1600 patients, with 10 different types of cancer, revealed that immune checkpoint inhibitors were more efficient as the tumor mutational burden (TMB) or foreignness of the cancer was increased." (PMID 32326073, 2020). "In addition, both CTLA-4 and PD-1 are currently being used as the targets of antibody-mediated functional blockade in human cancer immunotherapy." (PMID 32492969, 2020). "In addition, studies have applied epigenetics to determine mechanisms of resistance to cancer immunotherapies by characterizing chromatin regulators of intratumoral T cell dysfunction before and after PD-1, PD-L1, or CTLA-4 blockade therapy." (PMID 32793500, 2020). "Thus, identification of these immune checkpoint regulators, such as programmed cell death protein 1 (PD-1), cytotoxic T-lymphocyte-associated protein 4 (CTLA-4), and other inhibitory signaling, has created a new vision for cancer immunotherapy." (PMID 33117331, 2020). "The combination of cancer vaccines with checkpoint blockade (anti-CTLA-4, anti-PD-1) might strengthen the antitumor effects with stronger immune response but lower toxicity." (PMID 32158356, 2020). "CTLA4 transcripts were found at high levels in most cancer types." (PMID 31991588, 2020). "In murine cancer models, the gamma isoform of phosphoinositide 3-kinase (PI3Kγ), which is highly expressed in myeloid cells, can be targeted with a selective inhibitor that reprograms MDSCs and improves responses to antibodies targeting CTLA4, PD-1, or both." (PMID 32133005, 2020).
cancer (continued). "CTLA-4 is the first checkpoint protein blockade proven to be effective in cancer immunotherapy." (PMID 33553243, 2020). "Finally, GSEA results screened out several pathways involved in cancer progression, laying a solid foundation for the possible functional roles of CTLA4 or FGFR2 in HNSCC, encouraging more in-depth investigation in the future." (PMID 31894857, 2020). "Given the initial clinical successes achieved using PD1/PDL1 or CTLA4 antibody treatments in patients with cancer, the number of immunotherapy agents in clinical development is expanding rapidly with goals of improving the limited response rate and generating more durable responses." (PMID 32477338, 2020). "However, there is little information on CTLA4 and PD-1 expression levels and their clinical significance across diverse cancers." (PMID 33072070, 2020). "As a result, the effort to target CTLA-4 for cancer immunotherapy has stagnated." (PMID 31991588, 2020). "Furthermore, the inhibitor (ipilimumab) for cytotoxic T lymphocyte-associated antigen 4 (CTLA-4), which suppresses immune responses, has been approved for treating NSCLC and some other cancers." (PMID 31937321, 2020). "In addition to the ICIs discussed so far in this article, new antibodies are on the horizon that have shown promising results in other cancers: durvalumab and avelumab (both anti-PD-L1) and tremelimumab (anti-CTLA-4)." (PMID 33142689, 2020). "The correlation between PD-1/CTLA4 expression and cancer immunity was also analyzed." (PMID 33072070, 2020). "However, despite the unprecedented success of ICB in multiple cancer types, less than 20–30% of patients benefit from PD-1/CTLA-4 blockade." (PMID 33291616, 2020). "By targeting immune‐suppressive checkpoint molecules (e.g., PD1, PD‐L1, and CTLA‐4), immunotherapy rescued patients’ immune system and prevented cancer cells from evading the immune surveillance, and thus exerted a consistent antitumor efficacy for heterogenic patients." (PMID 33377634, 2020). "The five features we used to rank cancer types could also be used to evaluate whether an individual will be indicated for anti-CTLA-4 therapy in a personalized medicine approach." (PMID 31991588, 2020). "Furthermore, GVAX cancer vaccine combination therapy with anti-CTLA4, GM-CSF-activated dendritic cell-based antigen presentation, and other vaccinia-based treatments showed improved survival and immunogenicity." (PMID 32552802, 2020). "This is relevant because a deep characterization of immune infiltrate, conducted using public data to estimate the abundancies of immune-cell types, showed that CTLA-4-activated-like tumors present a conditional immune state similar to an escape phenotype exploited by cancer cells." (PMID 32850353, 2020). "Pan-cancer analyses can reveal the functional significance of PD-1 and CTLA4 in cancers." (PMID 33072070, 2020). "Moreover, nanodiscs in combination with anti-PD-1 and anti-CTLA-4 therapy revealed better eradication of established cancer cells." (PMID 33333816, 2020). "With the recent understanding on the critical significance of Treg depletion by ADCC/ADCP, and the effort to improve ADCC/ADCP activities of the new antibodies, a timely issue is which cancer types are most suitable for testing the new generation of anti-CTLA-4 antibodies." (PMID 31991588, 2020). "Blockade of CTLA-4 with antibody (ipilimumab) has improved T-cell function in various cancers." (PMID 32117298, 2020). "In cancer, CTLA-4 expression is induced in T cells after TCR activation and its signaling starts when APCs migrate from cancer to draining lymph nodes, here presenting the tumour-associated antigen to T lymphocytes, replacing CD28 by the interaction with B7 ligands." (PMID 33383673, 2020). "Cytotoxic T-lymphocyte-associated protein 4 (CTLA-4) and programmed cell death protein 1 (PD-1) are inhibitory checkpoints that are commonly seen on activated T cells and have been offered as promising targets for the treatment of cancers." (PMID 32580338, 2020).